AURKB (aurora kinase B)
Diseases named in the same sentence as AURKB in open-access papers (continued):
Sharing a sentence is not in itself a finding about the gene and the disease.
melanoma (continued). "The results showed that the apoptosis level was significantly increased by knocking down AURKB compared with shcontrol group in both vemurafenib-sensitive (A375, M249) and -resistant melanoma (A375R, M249R) cell lines." (PMID 32863956, 2020). "An anchorage-independent cell growth assay, flow cytometry, Western blot, and a xenograft mouse model were used to study the function of Aurora kinase B (AURKB) in both drug-sensitive and drug-resistant melanoma." (PMID 32863956, 2020). "A xenograft mouse experiment was conducted to determine the effect of AURKB on melanoma tumor growth in vivo." (PMID 32863956, 2020). "In melanoma cells, AURKB has been shown to induce senescence through the DDR and the transcription factor NF-κB41." (PMID 31000705, 2019). "We observed that the levels of both AURKA and AURKB were significantly higher in synchronized melanoma cell lines than in synchronized normal melanocytes." (PMID 23180582, 2013). "Also, HI-511, a dual inhibitor of AURKB and BRAF V600E achieved drug sensitivity in both susceptible and resistant melanoma cell growth." (PMID 33915740, 2021). "AURKB expression was previously reported as significantly elevated in melanoma metastases and here we report increased expression in primary melanomas." (PMID 34812139, 2021). "Additionally, AURKA and AURKB expression levels were significantly inversely correlated with T-cell markers in a dataset of melanoma samples derived from patients treated with anti-CTLA4 therapy." (PMID 33123754, 2021). "Notably, AURKB is expressed markedly higher in vemurafenib-resistant (A375R, M238R, and M249R) compared with vemurafenib-sensitive melanoma cell lines (A375, M238, and M249)." (PMID 32863956, 2020). "In this study, we identified AURKB as a critical target for drug-sensitive and - resistance melanoma treatment and found that HI-511 effectively suppressed development of vemurafenib-resistant melanoma by targeting both AURKB and BRAF V600E." (PMID 32863956, 2020). "All these results demonstrate that AURKB could be a potential target for melanoma treatment and in overcoming drug resistance." (PMID 32863956, 2020). "We attempted to identify the mechanism by which AURKB could mediate drug-sensitive and drug-resistant melanoma." (PMID 32863956, 2020). "This xenograft mouse model showed that HI-511 could suppress both vemurafenib-sensitive and -resistant melanoma growth through the inhibition of AURKB and BRAF V600E." (PMID 32863956, 2020). "Analysis of databases revealed the important role of AURKB in melanoma development." (PMID 32863956, 2020). "Overall, knocking down the expression of AURKB could suppress both vemurafenib-sensitive and -resistant melanoma cell growth and induce apoptosis through the mediation of the BRAF/MEK/ERKs and PI3-K/AKT pathways." (PMID 32863956, 2020). "Additionally, AURKB is expressed significantly higher in melanoma tissues compared with normal tissues (normal, n = 558, tumor, n = 461)." (PMID 32863956, 2020). "Consequently, partially silencing AURKB induced apoptosis in both vemurafenib-sensitive and -resistant melanoma cell lines equally." (PMID 32863956, 2020). "All these results indicate that AURKB could be a potential target for melanoma treatment and in overcoming drug resistance." (PMID 32863956, 2020). "Furthermore, we found that knocking down AURKB significantly suppressed melanoma cell growth in an anchorage-independent growth assay." (PMID 32863956, 2020). "Since our data suggest that loss of MIR211-5p and MIR328-3p expression and restoration of AURKB expression is concurrent with progression to melanoma, identification of the source of cell-extrinsic signals might suggest new strategies for chemoprevention or therapy." (PMID 34812139, 2021). "Our findings suggest that AURKB could be a potential target for melanoma treatment." (PMID 32863956, 2020). "Our results demonstrated that AURKB could be a potential target for melanoma treatment." (PMID 32863956, 2020).
melanoma (continued). "In other cancer types (NSCLC and melanoma), FOXM1 and AURKB have been reported to suppress immune cell activation." (PMID 40630538, 2025). "Taken together, these data demonstrate that AURKB inhibition limits the rate of BRAFV600E-induced proliferation in human melanocytic nevi and melanomas." (PMID 34812139, 2021). "Taken together, these data demonstrate an inverse expression between two miRNAs (MIR211-5p and MIR328-3p) and two targeted mRNAs (AURKB and GPR3) that toggles concurrently with the transition of arrested melanocytic nevi to melanomas." (PMID 34812139, 2021). "In an independent, publicly available RNA sequencing dataset of patient-derived melanoma samples, AURKA, AURKB, and CDCA8 showed trends toward increased expression in patients who did not respond to anti-PD-1 therapy (progressive disease)." (PMID 33123754, 2021). "The expression of both AURKB and GPR3 protein and mRNA was enriched in melanomas as compared to nevi." (PMID 34812139, 2021). "Next, we injected another vemurafenib-sensitive (M249) or -resistant melanoma cell line (M249R) with or without partial silencing of AURKB into this xenograft mouse model." (PMID 32863956, 2020). "HI-511, a novel dual-target inhibitor against both AURKB and BRAF V600E, could achieve durable suppression of melanoma growth, even drug-resistant melanoma growth." (PMID 32863956, 2020). "The effects of knocking down AURKB and HI-511 treatment on wild-type BRAF melanoma cell line (SK-MEL-31) were detected by crystal violet staining assay, the results revealed that knocking down AURKB and HI-511 treatment could suppress SK-MEL- 31 growth." (PMID 32863956, 2020). "Notably, we developed a dual-target inhibitor against both AURKB and BRAF V600E, which suppresses both drug-sensitive and -resistant melanoma development." (PMID 32863956, 2020). "Although a recent study reported overexpression of AURKA and AURKB in human melanoma at the tissue level, it is possible that the elevated expression of AURKA and AURKB was due to the high proliferative capacity of cancer cells, since AURKs are expressed largely during cell division." (PMID 23180582, 2013). "Moreover, the Western blot results demonstrated that knocking down the expression of AURKB markedly suppressed activation of the BRAF/MEK/ERKs and PI3-K/AKT pathways in both vemurafenib-sensitive (A375 and M249) and vemurafenib-resistant melanoma cell lines (A375R and M249R)." (PMID 32863956, 2020). "Therefore, a dual-target inhibitor for both AURKB and BRAF V600E might be an effective approach for overcoming drug-resistant melanoma." (PMID 32863956, 2020). "Importantly, they also found that HI-511, a dual-target inhibitor against both AURKB and BRAF V600E, suppresses both drug-sensitive and -resistant melanoma development by inducing apoptosis and mediating the inhibition of the BRAF/MEK/ERKs and PI3K-AKT signaling pathways." (PMID 33490091, 2020). "Importantly, we found that HI-511, a novel dual-target inhibitor against AURKB and BRAF V600E, suppresses both vemurafenib-sensitive and vemurafenib-resistant melanoma growth in vitro and in vivo by inducing apoptosis and mediating the inhibition of the BRAF/MEK/ERKs and PI3K/AKT signaling pathways." (PMID 32863956, 2020). "To determine whether the AURKA inhibitor MLN8237 inhibits the activation of AURKA phosphorylation on threonine-288 (T288) in melanoma cells, we treated Hs294T cells with MLN8237 for 3 days and performed Western blot analysis for phospho-AURKA (T-288) or phospho-AURKB (T-232)." (PMID 23180582, 2013). "Both in that dataset and in an independent dataset of melanoma samples derived from patients treated with anti-PD-1 therapy, AURKA, AURKB, and CDCA8 expression were higher in tumors that did not respond to immunotherapy." (PMID 33123754, 2021).
prostate carcinoma (25 papers, 2015 to 2025). A carcinoma that arises from epithelial cells of the prostate gland. "This aligns with previous reports suggesting a direct association between AURKB expression and the malignancy of prostate cancer, impacting prostate cell proliferation." (PMID 37934606, 2024). "To further determine the correlation between BRCA2 mutations and AURKB expression in prostate cancer patients, we collected samples from prostate cancer patients with intact and mutant BRCA2, and analyzed the AURKB level using immunohistochemistry." (PMID 37934606, 2024). "This hypothesis arises from the notable overexpression of AURKB in prostate cancer, which is directly associated with the aggressiveness of the disease." (PMID 37934606, 2024). "We further substantiated in LNCaP cells that the microtubule instability resulting from BRCA2 deficiency could be effectively reversed in prostate cancer cells by use of a specific chemical inhibitor of AURKB." (PMID 37934606, 2024). "By using an in situ PLA, we investigated whether K63-linked polyubiquitination of AURKB could be visualized in tissues from patients with prostate cancer, ccRCC or lung adenocarcinoma." (PMID 35853811, 2022). "The results showed that the average mRNA levels of AURKB in BRCA2-deficient patient samples were significantly lower than those in BRCA2-proficient patient samples, especially in BRCA2-deficient prostate cancer patient samples." (PMID 37934606, 2024). "In the FH cohort, which included metastatic prostate cancer cases, AURKB expression was significantly upregulated in postchemotherapy prostate cancer tissues." (PMID 34593983, 2023). "Prognosis analysis using the TCGA prostate cancer dataset revealed that a higher AURKB expression was a poor prognostic factor for recurrence-free survival." (PMID 34593983, 2023). "AURKB–TβRI complexes in patient's tumor tissue sections correlated with the malignancy of prostate cancer." (PMID 35853811, 2022). "Aberrant and high expression of AURKB is frequent in prostate cancer as well as other cancer forms, while the precise mechanisms of regulation of AURKB expression and the role of AURKB kinase activity remain to be elucidated." (PMID 35853811, 2022). "The amount of TβRI and AURKB complexes were more frequently observed in sections from prostate cancer patients with high Gleason score, which indicates more aggressive disease." (PMID 35853811, 2022). "High expression of AURKB and TβRI complexes visualized by in situ proximity ligation assay was present in clinical prostate cancer materials and correlated to poor prognosis." (PMID 35853811, 2022). "Of note, high expression of AURKB mRNA also correlated with poor prognosis in prostate cancer, ccRCC, and lung adenocarcinoma." (PMID 35853811, 2022). "High number of AURKB and TβRI complexes were found in clinical materials of prostate cancer patients with high Gleason Score, indicative of a poor prognosis." (PMID 35853811, 2022). "We found that RB1 is deleted in 10% of prostate cancers and intriguingly, that expression of AURKB is negatively correlated with RB1 in prostate cancer." (PMID 35853811, 2022). "Higher expression of AURKB also indicated poorer patient survival and more aggressiveness of prostate cancer." (PMID 35853811, 2022). "AURKB expression correlated with the degree of malignancy of prostate cancer, as determined by the Gleason score, based on histopathological scoring in prostate cancer samples (a higher Gleason score indicates more aggressive disease)." (PMID 35853811, 2022). "In prostate cancer, cyclin K was shown to mediate proliferation and inhibit apoptosis likely through AURKB." (PMID 33915740, 2021). "AURKB overexpression was found to be increased in prostate cancer tissues compared to healthy controls." (PMID 33915740, 2021). "Next, we further analyzed whether AURKB mRNA levels affect the prognosis of prostate cancer patients depending on BRCA2 status." (PMID 37934606, 2024).
prostate carcinoma (continued). "Similarly, Hongo observed elevated AURKB expression in prostate cancer tissues compared to adjacent normal tissues, with higher expression levels associated with a negative impact on recurrence‐free survival prognosis." (PMID 38898693, 2024). "AURKB exhibits high expression levels in primary human prostate cancer (PCa) and its cell lines." (PMID 38877472, 2024). "Compared with healthy controls, AURKB overexpression in prostate cancer tissues was increased, which was directly related to the malignancy of prostate cancer, and in vitro experiments confirmed that AURKB affected the proliferation level of prostate cancer cells." (PMID 37318676, 2023). "Higher AURKB expression was reported in prostate cancers with a high Gleason grade." (PMID 34593983, 2023). "We investigated whether AURKB was a potential target for the treatment of CBZ-resistant prostate cancer." (PMID 34593983, 2023). "Pimozide could be a promising drug to overcome taxane cabazitaxel (CBZ) resistance in docetaxel-resistant prostate cancer (CRPC) patients by targeting AURKB and KIF20A." (PMID 36798768, 2023). "CBZ-resistant prostate cancer tissues in our institution had higher AURKB and KIF20A expression." (PMID 34593983, 2023). "AURKB is frequently overexpressed in various cancers, including prostate cancer." (PMID 35853811, 2022). "We therefore investigated the expression of RB1 and AURKB in prostate cancer tissues." (PMID 35853811, 2022). "The identification of complexes between AURKB and TβRI may be a useful predictive biomarker in tumor tissues from patients with aggressive prostate cancer." (PMID 35853811, 2022). "We have previously identified AURKB as a HOXB13 transcriptional target in prostate cancer." (PMID 31273254, 2019). "Moreover, we also identified a significantly higher number of AURKB and TβRI complexes in sections from patients with aggressive prostate cancer compared to those from patients with less aggressive disease; in normal prostate tissues almost no signals were observed." (PMID 35853811, 2022). "Previous studies have highlighted that the expression of AURKB is connected to the prognosis of malignancies such as NSCLC12 and prostate cancer." (PMID 38898693, 2024). "Among these genes, expressions of AURKB and KIF20A was a significantly poor prognostic factors for prostate cancer recurrence, and we focused on these two genes." (PMID 34593983, 2023). "Immunostaining experiments performed in PC-3U prostate cancer cells and KELLY neuroblastoma cells revealed that TβRI co-localized with AURKB in the midzone, as well as in the midbody." (PMID 35853811, 2022). "MYC, ATF3, PMEPA1, AURKB, and HMOX-1 were identified as novel targets of curcumin in both less aggressive and highly aggressive metastatic prostate cancer cells in our study." (PMID 31581661, 2019). "Higher expression of AURKB and KIF20A was a poor prognostic factor of TGCA prostate cancer cohort." (PMID 34593983, 2023). "AURKB and KIF20A were highly expressed in cabazitaxel-resistant prostate cancer cells." (PMID 36798768, 2023). "Earlier work has shown that knockdown of AURKB in LNCaP, a human androgen-dependent prostate cancer cell line, does not affect tumor cell survival." (PMID 35853811, 2022). "However, there are no reports that describe how AURKB contributes to CBZ resistance in prostate cancer." (PMID 34593983, 2023). "Aurora kinase family members AURKA, AURKB and AURKC, have key functions to control mitotic progression in normal cells and are frequently overexpressed and dysregulated in several forms of cancer, including prostate cancer, contributing to progression of the disease." (PMID 35853811, 2022).
prostate carcinoma (continued). "In contrast, knockdown of AURKB in the more aggressive, androgen-independent PC3 cell line, results in apoptosis in vitro and reduced tumor growth in a xenograft nude mouse model in vivo, suggesting an important role for AURKB in androgen-independent prostate cancer cells." (PMID 35853811, 2022).
hepatocellular carcinoma (18 papers, 2010 to 2025). A malignant tumor that arises from hepatocytes. "In this study, we focused on the mechanism of AURKB in hepatocellular carcinoma (HCC) progression and on AURKB’s value as a diagnostic and prognostic biomarker in HCC." (PMID 38396874, 2024). "Similarly, in hepatocellular carcinoma, AURKB mRNA levels are significantly elevated in tumor tissues and serve as an independent prognostic marker for disease aggressiveness." (PMID 40710353, 2025). "We previously documented that hepatitis C virus (HCV) infection of human hepatoma Huh-7.5 cells results in a core protein-mediated decrease of Aurora kinase B (AURKB) activity and phosphorylation of Serine 10 in histone H3 (H3Ser10ph) levels, with an affectation of inflammatory pathways." (PMID 36992689, 2023). "AURKB is also upregulated and hypomethylated in hepatocellular carcinoma." (PMID 31889904, 2019).
osteosarcoma (18 papers, 2014 to 2025). A usually aggressive malignant bone-forming mesenchymal neoplasm, predominantly affecting adolescents and young adults. "Based on our findings, Rsk2 and/or Aurora kinase B can serve as potential targets for the design of new osteosarcoma therapies." (PMID 40634321, 2025). "Next, we used three inhibitors (Dinaciclib, Alisertib, or Barasertib), which targeted the top candidate hits (CDK members, AURKA, or AURKB) to validate the screen results in multiple osteosarcoma cell lines." (PMID 37419907, 2023). "Another report shows AURKB knockdown resulted in a reduction in migratory and invasive ability of osteosarcoma cell line by through mTOR/ULK1 pathway." (PMID 35332150, 2022). "AURKB is a serine/threonine kinase that has been proposed to stimulate the invasion and proliferation of osteosarcoma through PTK2/PI3K/AKt/NF-κB signaling pathway and VCP." (PMID 33858425, 2021). "In the PPI network, we selected six genes (CDK1, CCNB2, CDC20, CCNA2, BUB1, and AURKB) as the core STIL differentially co-expressed genes in osteosarcoma." (PMID 33858425, 2021). "Using the 13 gene chips, we found that six hub differentially co-expressed genes (CDK1, CCNB2, CDC20, CCNA2, BUB1, and AURKB) were highly expressed in osteosarcoma." (PMID 33858425, 2021). "Inhibition of AURKB has been shown to suppress osteosarcoma and HepG2 cell migration and invasion, while overexpressed AURKB localises to the nucleus and cortical actin filaments of interphase normal rat kidney cells." (PMID 31142743, 2019). "Inhibition of AURKB can suppress the proliferation of osteosarcoma cells." (PMID 34838000, 2021). "In particular, CNV was more frequent in CCND3, AURKB, CCNE1, GID4, and MYC in P-AYA, while MDM2, CDKN2A/B, and FRS2 were more frequently altered in adult osteosarcoma (p < 0.001)." (PMID 35705558, 2022). "Thus, AURKB inhibitors may also provide a new option for the treatment of osteosarcoma." (PMID 33858425, 2021). "RecQL4-mediated regulation of AURKB expression was next investigated in RecQL4-silenced hTERT-immortalized (HMEC-hT1) and malignantly transformed osteosarcoma cells (U2OS)." (PMID 30206236, 2018). "STIL is associated with osteosarcoma proliferation and invasion, and may be promote the progression of osteosarcoma by regulating the expression of CDK1, CCNB2, CDC20, CCNA2, BUB1 and AURKB." (PMID 33858425, 2021). "Moreover, the bioinformatics analysis showed that STIL may participate in the biological function of osteosarcoma by regulating CDK1, CCNB2, CDC20, CCNA2, BUB1, and AURKB." (PMID 33858425, 2021).